VCAM1 (vascular cell adhesion molecule 1)
Diseases named in the same sentence as VCAM1 in open-access papers (continued):
Sharing a sentence is not in itself a finding about the gene and the disease.
colorectal cancer (27 papers, 1998 to 2025). A primary or metastatic malignant neoplasm that affects the colon or rectum. "Overexpression of VCAM-1 in colorectal cancer cells is closely associated with the invasive and aggressive clinical characteristics and poor prognosis of colorectal cancer patients." (PMID 36979820, 2023). "VCAM-1 is a molecule that is expressed in colorectal cancer; it is associated with the presence of CD3+ lymphocytes and participates in tumor infiltration by immune cells." (PMID 37569878, 2023). "This situation is similar in the case of colorectal cancer, where the over-expression of the VCAM-1 gene is associated with metastasis and progression of this cancer." (PMID 35742950, 2022). "In this study, it was shown that TAMs were enriched in colorectal cancer, and their infiltration was associated with VCAM-1 expression." (PMID 30894509, 2019). "In addition, VCAM-1 is overexpressed in colorectal cancer, and is associated with lymph node metastasis, clinical stage, and tumor progression in patients with colorectal cancer." (PMID 29614819, 2018). "Vcam1, vascular cell adhesion molecule 1, promotes tumor cell invasion and metastasis in colorectal cancer." (PMID 40282557, 2025). "Despite the promise of other ASOs in cancer models, VCAM-1 ASOs have yet to be investigated in experimental models of colorectal cancer." (PMID 40095109, 2025). "Data analysis from TCGA and Gene Expression Omnibus databases showed that high VCAM-1 expression was correlated with metastasis and short survival in colorectal cancer patients." (PMID 39160581, 2024). "VCAM-1 has also been reported as an influential factor in the invasion and metastasis of colorectal cancer cells by facilitating the formation of pseudopodia and invadopodia to cross the vessel wall." (PMID 39160581, 2024). "VCAM1 is an important member of the immunoglobulin superfamily and promotes the invasion and metastasis of colorectal cancer by inducing transendothelial migration." (PMID 37511481, 2023). "High serum levels of VCAM-1 have also been identified in colorectal cancer patients compared with healthy controls." (PMID 36497180, 2022). "Human colorectal cancer-derived CAFs can drive the adhesion of monocytes by up-regulating VCAM-1 levels in colorectal cancer cells." (PMID 34680425, 2021). "As an important member of CAMs, however, the role of VCAM-1 in the development of colorectal cancer is still unclear." (PMID 32793471, 2020). "Human colorectal cancer-derived CAFs can promote the adhesion of monocytes by up-regulating VCAM-1 expression in colorectal cancer cells." (PMID 30894509, 2019). "Serum concentrations of ICAM-1 and VCAM-1 were significantly elevated in the patients with colorectal cancer in comparison with a group of healthy subjects (P < 0.00001)." (PMID 9667659, 1998). "It is well established that VCAM1 promotes transendothelial migration in colorectal cancer, which could be a mechanism behind vascular invasion." (PMID 40650042, 2025). "Furthermore, VCAM-1 is involved in tumor metastasis, as it has been described in lung and colorectal cancers." (PMID 39596815, 2024). "Additionally, ST3GAL6-AS1 was co-expressed with a variety of mRNAs, including PECAM1, VCAM1, CXCL12, CD34, CDH5, and VWF, and was associated with colorectal cancer progression." (PMID 33790949, 2021). "However, the molecular role and mechanism of VCAM1 in the regulation of the progression of colorectal cancer (CRC) has rarely been studied." (PMID 32793471, 2020). "In addition, the expression levels of VCAM1 are positively correlated with variously differentiated colorectal cancer." (PMID 32793471, 2020). "Our further study proved that VCAM1 could stimulate the TEM of colorectal cancer cells, as detected by a Matrigel-coated Transwell assay." (PMID 32793471, 2020).
colorectal cancer (continued). "Interestingly, imaging assessment of VCAM-1 density before treatment initiation has resulted in information about the T-cell infiltration within the tumor vasculature and about the response to PD-L1 blockade in preclinical models of colorectal cancer." (PMID 39596815, 2024). "Additionally, in a colorectal cancer model, it has been described that CAFs can affect tumor infiltration of inflammatory cells by promoting upregulation of cell adhesion molecules such as VCAM-1 in cancer cells." (PMID 31108906, 2019). "In human ex vivo colorectal cancer tumour explants, Q8 significantly decreased the secretion of both TIE-2 and VCAM-1 expression." (PMID 31217905, 2019). "Recent studies have indicated that the serum ICAM-1 and/or VCAM-1 are increased in HCC, breast and colorectal cancer." (PMID 24555415, 2014).
ischemia (27 papers, 2011 to 2025). A hypoperfusion of the BLOOD through an organ or tissue caused by a PATHOLOGIC CONSTRICTION or obstruction of its BLOOD VESSELS, or an absence of BLOOD CIRCULATION. "ROS induce intercellular adhesion molecule-1 (ICAM-1) and vascular cell adhesion molecule-1 (VCAM-1) which recruit leukocytes to the region with ischemia/reperfusion injury and cause a secondary disorder." (PMID 30513734, 2018). "TNFα and IL-1 have been shown to cause up-regulation of E-selectin, ICAM-1, ICAM-2, and VCAM-1 on cerebral endothelial cells and the induction of such adhesion molecules may explain the elevation of TNFα and IL-1 levels after ischemia increases neutrophil infiltration." (PMID 22196138, 2011). "Vcam1 levels were upregulated in a murine model of vascular dementia, and inhibition of Vcam1 reduces ischemia-induced neuroinflammation and cognitive dysfunction." (PMID 39456952, 2024). "VCAM-1 has been reported to mediate hematopoietic stem cell recruitment to the injury site through the VLA-4 pathway in mice during partial hepatic ischemia–reperfusion (IR) injury, and this effect can be abrogated by blocking VCAM-1." (PMID 35222039, 2022). "Although it has been reported that compared with ICAM-1, the increased expression of VCAM-1 is more closely related to the degree of ischemia and hypoxia of the retina and the formation of NPAs and NV." (PMID 35967519, 2022). "Pioglitazone was found to inhibit TNFα-induced expression of ICAM-1 and VCAM-1 in activated cultured endothelial cells and an ischemia/reperfusion renal injury model." (PMID 34831270, 2021). "Animal studies have also demonstrated that XFZY can lower intracellular adhesion molecule-1 (ICAM-1) and vascular cell adhesion molecule-1 (VCAM-1), thus reducing inflammatory reactions triggered by ischemia-reperfusion injury (IRI)." (PMID 32934661, 2020). "SMI also inhibited expression of ICAM-1 and vascular cell adhesion molecule 1 (VCAM-1) to alleviate inflammatory infiltration following ischemia/reperfusion, and alleviated myocardial ischemia/reperfusion injury caused by multiple inflammatory responses." (PMID 32848729, 2020). "Next, we investigated the expression of ICAM-1 and VCAM-1 in the dorsal skinfold chamber tissue after 3 h ischemia and 3 h reperfusion by means of Western blot." (PMID 30992483, 2019). "VCAM-1, on the other hand, is expressed on the cytokine-activated endothelium, attracting neutrophils to damaged myocardium and mediating ischemia reperfusion injury." (PMID 28850583, 2017). "Here, we report the temporal expression pattern of VCAM-1 in the microcirculation of porcine ischemia-reperfusion impaired myocardium." (PMID 28628621, 2017). "In immunofluorescence staining, expression levels of ICAM-1 and VCAM-1 were significantly decreased in the microvessels of the Sac-1004-ischemia group 3 h after I/R compared with those in the vehicle-ischemia group." (PMID 28645333, 2017). "VCAM-1+CV-MSCs possessed a favorable angiogenic paracrine activity and displayed therapeutic efficacy on hindlimb ischemia." (PMID 27044487, 2016). "Results demonstrated that VCAM-1+CV-MSCs significantly augmented the generation of collateral vessels at the ischemia site (n = 3–5, *p <0.05), whose angiography score was 1.52-fold and 1.28-fold higher than the PBS and VCAM-1−CV-MSCs groups, respectively." (PMID 27044487, 2016). "Besides, the authors identified that VCAM-1+ MSCs exerted more therapeutic effects on ischemia site, which were evaluated by the ischemia restoration and the formation of collateral vessels." (PMID 34823579, 2021). "Adhesion molecules (Icam-1 and Vcam-1) reflect the reperfusion phase of inflammatoryreaction to ischemia in which leukocytes adhere to the endothelium, increasingvessel permeability, amplifying the inflammatory reaction by the migration of moreinflammatory cells." (PMID 34755767, 2021).
ischemia (continued). "Suppressing the inflammatory response in mouse hindlimb post the tourniquet-induced ischemia-reperfusion; Reducing tissue edema, inflammatory exudate formation, and leukocyte infiltration; Decreasing the expression of VCAM-1, and E-selectin in the hindlimb tissue post ischemia-reperfusion." (PMID 33553219, 2020). "ICAM‐1 and VCAM‐1 are the adhesive molecules that also play a regulatory role during inflammation, mediated leukocyte migration into the injured CNS, and contribute to ischemia‐induced neuroinflammation." (PMID 29201553, 2017). "Our findings indicate that LOX-1 plays an important role in ischemia-induced angiogenesis by 1) Nox2-ROS-NF-κB activation, 2) upregulated expression of adhesion molecules: VCAM-1 and LOX-1 and 3) promoting macrophage infiltration, which expresses angiogenic factor VEGF." (PMID 25514797, 2014). "In this study, we have firstly demonstrated that the VCAM-1+CV-MSC subpopulation displayed a potent angiogenic property and exerted enhanced therapeutic efficacy on regeneration after ischemia in comparison with the VCAM-1−CV-MSC subpopulation." (PMID 27044487, 2016). "In the immediate aftermath of ischemia, endothelial cells begin to upregulate the expression of adhesion molecules, such as intercellular adhesion molecule 1 (ICAM-1), vascular cell adhesion molecule 1 (VCAM-1), P-selectin, and E-selectin." (PMID 39582857, 2024). "Furthermore, the expressions of HIF-1a, VEGF, PDGF, VCAM-1, and ICAM-1 mRNA were all significantly increased in WIRS control group, signifying that pathogenesis of WIRS was related to ischemia and defective blood supply." (PMID 32801474, 2020). "Its expression is rapidly induced by ischemia–reperfusion injury, promoting leukocyte adhesion to ECs via the Janus kinase 2 (JAK2)-signal transducer and activator of transcription 3 (STAT3) pathway by upregulating vascular cell adhesion molecule-1 (VCAM-1) expression." (PMID 40332339, 2025). "Similarly, ICAM-1 and VCAM-1 mRNA levels were increased in the brain tissue of Poldip2+/+ mice after ischemia, but not in Poldip2+/− mice." (PMID 33692398, 2021).
preeclampsia (26 papers, 2010 to 2025). Preeclampsia is a hypertensive disorder of pregnancy that is characterized by new-onset hypertension with proteinuria presenting after 20 weeks of gestation, and depending on mild or severe forms may initially present with severe headache, visual disturbances, and hyperreflexia. "This study investigates the associations of ICAM-1, VCAM-1, and E-selectin gene variants (rs3093030, rs3783605, and rs1805193, respectively) with preeclampsia comorbid with HIV infection in women of African ancestry." (PMID 39409189, 2024). "Single-nucleotide polymorphisms of ICAM-1, VCAM-1, and E-selectin will have downstream effects on their release into circulation, thus affecting placentation in preeclampsia." (PMID 39409189, 2024). "Intercellular adhesion molecule-1 (ICAM-1), vascular adhesion molecule-1 (VCAM-1), and E-selectin are cell adhesion molecules that play a significant role in inflammation and are implicated in the pathophysiology of preeclampsia development and HIV infection." (PMID 39409189, 2024). "Since cell invasion requires proteolysis of the extracellular matrix, dysregulation of the cell adhesion molecules ICAM-1, VCAM-1, and E-selectin are implicated in preeclampsia development." (PMID 39409189, 2024). "High maternal serum VCAM-1 and E-selectin levels in preeclampsia pregnancies was associated with 60%–70% decrease in NO level in the fetal endothelium." (PMID 36420416, 2022). "Among these genes, LAMB2, PTK2, RAC1, QSOX1, FN1, and VCAM1 have known associations with the pathogenic mechanisms of preeclampsia." (PMID 35719905, 2021). "Additionally, the C allele of the ICAM-1 (rs3093030 C>T) and G allele of the VCAM-1 (rs3783605 A>G) genes were found to have a greater role in the co-morbidity and may be considered as a risk factor for preeclampsia development in women of African ancestry." (PMID 39409189, 2024). "More specifically, the immune expression of ICAM-1, VCAM-1, and E-selectin within cyto- and syncytiotrophoblast cells are dysregulated in preeclampsia, indicating their role in defective placentation." (PMID 39409189, 2024). "It is widely accepted that ICAM-1, VCAM-1, and E-Selectin are dysregulated, thereby affecting trophoblast invasion and angiogenesis, the hallmarks of preeclampsia development." (PMID 39409189, 2024). "They found that TGF-β1 levels were significantly higher in the preeclampsia group than the control group, while E-selectin and VCAM-1 levels were significantly lower.However, several other studies have diverged from our observation of TGF-β1." (PMID 37700972, 2023). "Among these markers, for example, vascular cell adhesion protein 1 (VCAM-1) has previously been shown to be reduced in pregnancies complicated by preeclampsia or intrauterine growth restriction and regulate the invasion ability of HTR-8 cells in vitro." (PMID 35292627, 2022). "It was demonstrated that the neonates of mothers with preeclampsia had higher VCAM-1 expression in their umbilical arteries and larger coronary arteries, suggesting that coronary artery size is an indicator of neonatal endothelial inflammation." (PMID 36420416, 2022). "VCAM1 has become the subject of many studies in terms of its involvement in the pathophysiology of preeclampsia." (PMID 35406725, 2022). "For instance, elevated plasma levels of PTX3 associate to VCAM-1, flow-mediated dilatation and cardiovascular outcomes in CKD patients, as well as with altered endothelial function during preeclampsia." (PMID 23658833, 2013). "In this study, significant correlations were found between IP-10, MCP-1 and VCAM-1 levels and endothelial markers in normal pregnancy and preeclampsia." (PMID 21126355, 2010). "Circulating levels of the pro-inflammatory cytokines IL-6 and TNF-α, the chemokines IL-8, IP-10 and MCP-1, as well as the adhesion molecules ICAM-1 and VCAM-1, were raised in preeclampsia compared with healthy pregnancy, resulting in an overall pro-inflammatory systemic environment." (PMID 21126355, 2010).
preeclampsia (continued). "In our study, the strong association of AA in preeclamptic vs. normotensive pregnancies may be due to the elevated VCAM-1 levels present during pregnancy and preeclampsia, implying a possible mechanism by which endothelial cells attract leukocytes and cause endothelial cell damage." (PMID 39409189, 2024). "Increases in in adiponectin levels in preeclampsia have anti-inflammatory, and vascular protective activities and lead to decreased expression of cell adhesion molecules (E-selectin, ICAM-1, VCAM-1), and suppression of vascular inflammation." (PMID 37964253, 2023). "Vascular Cell Adhesion Molecule 1 (VCAM1) is involved in cellular adhesion and serum concentrations of sVCAM-1 are significantly elevated in both mild and severe preeclampsia." (PMID 35719905, 2021). "We have confirmed that this is also likely in preeclampsia in our functional experiments, demonstrating that placental factors or TNFα significantly reduced endothelial GATA2 coincident with increased VCAM-1 expression." (PMID 30659233, 2019). "S1P also induces the activation of inflammatory mediators, such as VCAM-1, ICAM-1 and COX, which are elevated in both blood and placenta during preeclampsia." (PMID 28542236, 2017). "Elevated circulatory VCAM-1, MCP-1 and IP-10 were found in pregnant women with preeclampsia." (PMID 41394354, 2025). "Forty women with preeclampsia and matched controls were analyzed for ICAM-1, VCAM-1 and E-selectin." (PMID 22952728, 2012).